ANGPTL4 (angiopoietin like 4)
Diseases named in the same sentence as ANGPTL4 in open-access papers (continued):
Sharing a sentence is not in itself a finding about the gene and the disease.
cutaneous melanoma (2 papers, 2017 to 2021). A primary melanoma arising from atypical melanocytes in the skin. "Forced over-expression of ANGPTL4 in cutaneous melanoma cells promoted their ability to adhere and transmigrate brain endothelial cells." (PMID 29100268, 2017). "This study showed that ANGPTL4 is more highly expressed in MBM cells than in corresponding cutaneous melanoma cells in human MBM models as well as in clinical samples." (PMID 29100268, 2017). "To this end we compared RPPA data of ANGPTL4 overexpressing (ANGPTL4hi) cutaneous melanoma cells and MBM cells with the corresponding control (CONpQC) cells." (PMID 29100268, 2017). "Nude mice were inoculated orthotopically with control (CONpQC) cutaneous melanoma cells or with cells overexpressing ANGPTL4 (ANGPTL4hi )." (PMID 29100268, 2017). "Taken together these results demonstrated that ANGPTL4 expressed by cutaneous melanoma cells induces or up-regulates secretion of soluble factors that inhibit BEC growth." (PMID 29100268, 2017). "Stimulation of BEC with CM of ANGPTL4 over-expressing cutaneous melanoma cells down-regulated the expression of CLDN1, a TJ protein involved in cell adhesion." (PMID 29100268, 2017). "However ANGPTL4 overexpressing cutaneous melanoma cells are sensitive to the cytotoxic activity of BDF which would diminish metastasis." (PMID 29100268, 2017). "We next asked whether ANGPTL4 over-expression in cutaneous melanoma cells would influence the capacity of such cells to form spontaneous brain micro-metastasis." (PMID 29100268, 2017). "In vivo data indicated that forced overexpression of ANGPTL4 promoted the tumorigenicity of cutaneous melanoma cells but did not increase their ability to form brain metastasis." (PMID 29100268, 2017).
dementia (2 papers, 2024 to 2025). Loss of intellectual abilities interfering with an individual's social and occupational functions. "Thirteen of the 19 (68%) candidate proteins were significantly associated with incident all-cause dementia, including three of the top four risk proteins for APOEε4 carriers, ANGPTL4, PTX3, and NfL." (PMID 39482741, 2024). "An effect of PCSK9, ANGPTL4, and LPL variants on dementia risk cannot be excluded." (PMID 41059729, 2025). "Plasma ANGPTL4 most strongly discriminated resilient from non-resilient APOEε4 carriers in our discovery analysis and replicated in our analyses of 14-year dementia risk." (PMID 39482741, 2024).
dengue (2 papers, 2014 to 2025). "The association between plasma ANGPTL4 concentration and plasma leakage was analyzed in 48 dengue patients during the acute phase." (PMID 40006981, 2025). "Lastly, our use of multivariable models adjusted for demographics and comorbidities suggested that ANGPTL4 has an independent association with dengue severity, strengthening the potential significance of our findings." (PMID 40006981, 2025). "When analyzed as a continuous variable, each doubling of the ANGPTL4 concentration was associated with an aOR of 1.18 (95%CI: 0.95–1.47, p = 0.139) for severe dengue, further supporting this trend." (PMID 40006981, 2025). "This study investigated the association between plasma ANGPTL4 levels and dengue severity in Singapore adults." (PMID 40006981, 2025). "Notably, the upper bounds of the confidence intervals revealed an increasing trend across tertiles, suggesting a potential association between higher ANGPTL4 levels and greater dengue severity." (PMID 40006981, 2025). "Notably, 8 out of 11 patients (72.72%) with high ANGPTL4 levels (above the mean level of 5122.3 pg/mL) developed severe dengue or dengue hemorrhagic fever with warning signs, suggesting a potential association between plasma ANGPTL4 and dengue severity, particularly in relation to vascular leakage." (PMID 40006981, 2025). "Examining ANGPTL4 in relation to other related angiopoietin proteins and cytokines previously implicated in dengue and other flaviviral diseases may also provide important insights into dengue pathogenesis." (PMID 40006981, 2025). "Secondly, our study compared plasma ANGPTL4 concentrations in dengue patients versus healthy controls, thus facilitating meaningful comparisons and establishing baseline levels." (PMID 40006981, 2025). "Angiopoietin-like protein 4 (ANGPTL4) regulates vascular permeability, but its role in dengue pathogenesis is unclear." (PMID 40006981, 2025). "The ANGPTL4 continuous level analysis revealed a trend toward an increased probability of severe dengue with higher plasma ANGPTL4 (aOR = 1.18, 95% CI: 0.95–1.47), albeit statistically non-significant (p = 0.139)." (PMID 40006981, 2025). "Given its potential importance in vascular dysfunction and the critical role of vascular leakage in severe dengue, it is essential to investigate the relationship between ANGPTL4 and dengue severity in humans." (PMID 40006981, 2025). "Plasma ANGPTL4 levels were significantly higher in dengue patients than controls, suggesting its potential as a biomarker, which warrants future detailed investigations." (PMID 40006981, 2025). "The objective of this study was to measure the levels of ANGPTL4 in blood samples from dengue patients compared to healthy controls and to explore its involvement in dengue virus infection." (PMID 40006981, 2025). "In conclusion, this study revealed that plasma ANGPTL4 levels were significantly elevated in dengue patients compared to healthy subjects." (PMID 40006981, 2025). "Plasma ANGPTL4 levels were significantly elevated during acute dengue (4634.3 pg/mL) versus healthy controls (907.4 pg/mL), declining during convalescence." (PMID 40006981, 2025). "In the acute phase, severe dengue cases had a median ANGPTL4 concentration of 677.4 pg/mL (IQR: 416.4 to 3206.1), while non-severe cases had a median of 909.1 pg/mL (IQR: 569.9 to 5679.0)." (PMID 40006981, 2025). "We conducted further detailed analysis of the clinical and laboratory parameters of 11 patients who were all above the mean ANGPTL4 levels of 5122.3 pg/mL for acute samples of severe dengue patients." (PMID 40006981, 2025). "The rising ANGPTL4 levels exhibit a concentration-dependent effect on vascular permeability, potentially contributing to the vascular leakage seen in severe dengue." (PMID 40006981, 2025).
dengue (continued). "These disease severity patterns among a significant proportion of patients with very high ANGPTL4 levels suggest the potential role of ANGPTL4 and its utility as an early biomarker of dengue disease progression and warrant future detailed studies." (PMID 40006981, 2025). "In dengue patients, acute phase ANGPTL4 levels are highly significantly elevated compared to healthy controls (p < 0.0001) while convalescent phase levels are higher but not statistically significant (p = 0.128)." (PMID 40006981, 2025). "Although not statistically significant, these trends warrant further investigations into the potential relationship between ANGPTL4 and dengue severity." (PMID 40006981, 2025). "Increased cleavage and endothelial binding in severe dengue may lead to lower circulating ANGPTL4 levels despite higher overall activity." (PMID 40006981, 2025). "Understanding the role of ANGPTL4 in dengue pathogenesis may offer new insights into disease mechanisms and potentially novel management strategies." (PMID 40006981, 2025). "Larger prospective studies with serial sampling, including pediatric populations, may clarify the role of ANGPTL4 in severe dengue." (PMID 40006981, 2025). "Furthermore, plasma ANGPTL4 was significantly elevated in acute dengue (mean 4634.3 pg/mL) versus healthy controls (mean 907.4 pg/mL), with declining levels in the convalescent phase." (PMID 40006981, 2025). "Additionally, our analysis lacked plasma samples at multiple time-points throughout the acute and convalescent dengue phases, limiting our ability to determine the temporal trends of ANGPTL4 levels during the progression from mild to moderate to severe dengue." (PMID 40006981, 2025). "For better statistical power, larger prospective studies with an analysis of serial samples at multiple time-points are necessary to elucidate ANGPTL4 expression trends throughout dengue illness, DHF and DSS, including in pediatric cohorts where vascular permeability is a key concern." (PMID 40006981, 2025). "This suggests that ANGPTL4 may be relevant as a biomarker or therapeutic target, which warrants further investigations into the relationship between ANGPTL4 levels and dengue severity." (PMID 40006981, 2025). "ANGPTL4 levels were measured in the acute and convalescent phases of dengue." (PMID 40006981, 2025). "By examining the relationship between ANGPTL4 levels and clinical disease severity, we sought to enhance our understanding of dengue pathogenesis and contribute to developing improved diagnostic and therapeutic approaches for this significant disease of global concern." (PMID 40006981, 2025). "Future research may help to clarify the role of ANGPTL4 especially in severe dengue manifestations." (PMID 40006981, 2025). "Circulating levels of Angptl3 and Angptl4 have not previously been studied in dengue or leptospirosis." (PMID 24444080, 2014). "To investigate the role of ANGPTL4 in dengue and its severity, we utilized plasma samples of the CODEN cohort to examine ANGPTL4 levels in 48 dengue patients (24 severe and 24 non-severe cases) during acute and convalescent phases of dengue." (PMID 40006981, 2025).
disc degeneration (2 papers, 2025). "Fibroblastic NP cells were shown to upregulate matrix-remodeling genes such as HTRA1 (High-temperature requirement protein A1) and ANGPTL4 (Angiopoietin-like 4), markers associated with severe disc degeneration." (PMID 41155233, 2025). "Refined clustering and classification distinguished the fibrocyte-like populations as subtypes in the NP cells - and immunocytes-clusters, expressing disc degeneration markers HTRA1 and ANGPTL4 and genes related to response to TGF-β." (PMID 39828732, 2025).
gallbladder cancer (2 papers, 2021 to 2025). "ANGPTL4 was also differentially expressed in gallbladder cancer associated fibroblasts when compared to normal fibroblasts, as well as being co-localized with protein-1 and a-smooth muscle actin, reflecting the strong co-expression between ANGPTL4 and fibroblast markers." (PMID 40233044, 2025). "Finally, the ANGPTL4 expression was investigated in the stroma of different lesion tissues of the human gallbladder by immunohistochemistry, especially the expression in GCAFs in vivo by co‐immunofluorescence, and their prognostic significance in patients with gallbladder cancer (GBC) was assessed." (PMID 34331381, 2021).
Glomerular sclerosis (2 papers, 2020 to 2024). Accumulation of scar tissue within the glomerulus. "PPARγ agonists inhibit glomerular sclerosis by reducing ANGPTL4 levels, while PPARα reduces ANGPTL4 levels and relieves tubulointerstitial damage." (PMID 32280690, 2020). "Angptl4 ASO did not cause remarkable alterations in nondiabetic control mice, but caused significant reduction in fibrosis, collagen deposition, and glomerulosclerosis in diabetic mice, demonstrating that Angptl4 ASO improves the kidney phenotype." (PMID 39630889, 2024).
hypoglycaemia (2 papers, 2018 to 2025). "Accordingly, it is unlikely that the observed hypoglycaemia and hyperinsulinaemia in Angptl4−/− mice are linked to loss of inhibition of LPL activity in islet cells, whether via ANGPTL4 that is produced in the pancreas or elsewhere." (PMID 29502266, 2018). "It is demonstrated that hypoglycemia induces VSMC fibrosis in vivo, whereas Angptl4 knockdown can attenuate VSMC fibrosis in vitro." (PMID 40650639, 2025).
injury (2 papers, 2019 to 2025). Damage inflicted on the body as the direct or indirect result of an external force, with or without disruption of structural continuity. "Similarly, ANGPTL4 suppression by small interfering RNA (siRNA) also protects mice against lipopolysaccharide-induced acute lung injury." (PMID 31164474, 2019).
Lewis lung carcinoma (2 papers, 2014 to 2019). "Overexpression of ANGPTL4 can inhibit the motility, invasiveness and metastasis of Lewis lung carcinoma and mouse skin cancer cells." (PMID 25148701, 2014).
lichen planus (2 papers, 2022 to 2023). A chronic, recurrent, pruritic inflammatory disorder of unknown etiology that affects the skin and mucus membranes. "In this paper we analyzed only ANGPTL8; however, in our earlier study, we took into consideration ANGPTL4 in psoriatic patients, but also in lichen planus and vitiligo." (PMID 36983346, 2023).
liver cirrhosis (2 papers, 2021 to 2024). "In the clinical settings, a high serum ANGPTL4 protein level in HCC patients is predictive of liver cirrhosis and intrahepatic metastasis." (PMID 34540685, 2021). "Interfering with ANGPTL4 through the TLR4/NF-κB pathway can inhibit fibrosis in hepatic stellate cells and impede the progression of liver cirrhosis in mice." (PMID 38992710, 2024).
macular edema (2 papers, 2021 to 2024). "In the ophthalmology field, ANGPTL4 was first shown to be a possible vasoactive cytokine to facilitate vascular permeability and macular edema in patients with DR." (PMID 39768065, 2024).
malignant glioma (2 papers, 2013 to 2015). A grade III or grade IV glioma arising from the central nervous system. "The molecular mechanisms of Angptl4-induced angiogenesis in malignant gliomas still remain largely unknown." (PMID 23617883, 2013). "In summary, we demonstrated that EGFRvIII induces Angptl4 expression through the ERK/c-Myc pathway and promotes tumor angiogenesis in malignant gliomas." (PMID 23617883, 2013).
pheochromocytoma (2 papers, 2006 to 2010). "ANGPTL4 was strongly expressed in the peri-adrenal adipose tissue around a pheochromocytoma and in lipohypertrophic, in which adipose fat mass increases, suggesting that through secretion of angiogenesis modulators adipocytes may have autocrine effects on their own growth." (PMID 17049073, 2006).
serous ovarian cancer (2 papers, 2015). "This conclusion is supported by the association of high ANGPTL4 expression with a shorter relapse-free survival in serous ovarian carcinoma." (PMID 25968567, 2015). "The deregulation of ANGPTL4 is of particular interest, since its secreted product has been associated with cancer cell invasion and metastasis and is present in substantial amounts in the malignancy-associated ascites of most serous ovarian carcinoma patients." (PMID 25968567, 2015). "We therefore tested the Cancer Genome Atlas (TCGA) cohort of 506 high grade serous ovarian cancer patients for a potential link of ANGPTL4 expression to the clinical outcome of the disease." (PMID 25968567, 2015). "This was a novel finding, as there is no information in the literature regarding ANGPTL4 expression in serous ovarian cancer." (PMID 26205780, 2015).
thyroid cancer (2 papers, 2012 to 2023). "Upregulation of Angptl4 expression by bexarotene is in agreement with previous observations in thyroid cancer cell lines." (PMID 23056264, 2012).
vitiligo (2 papers, 2022 to 2023). Generalized well circumscribed patches of leukoderma that are generally distributed over symmetric body locations and is due to autoimmune destruction of melanocytes. "ANGPTL4 concentration was statistically significantly higher in patients with LP compared to the control group (p < 0.01); moreover, it was significantly higher than in psoriatic patients (p < 0.001) and patients with vitiligo (p < 0.01)." (PMID 36144281, 2022). "There was a positive correlation between ANGPTL4 concentration and fasting glucose (R = 0.43) and AST activity (R = 0.39) in psoriatic patients and ALT activity in patients with vitiligo (R = 0.44)." (PMID 36144281, 2022). "Moreover, there was a positive correlation between ANGPTL4 concentration and ALT activity in patients with vitiligo (R = 0.44)." (PMID 36144281, 2022).
Abdominal obesity (1 paper, 2020). Excessive fat around the stomach and abdomen. "Our results are in agreement with studies that demonstrate that ANGPTL-4 levels are positively correlated to BMI, abdominal obesity (by waist circumference) and fat mass." (PMID 32878157, 2020).
abnormal glucose tolerance (1 paper, 2020). "ANGPTL4 serum levels are significantly higher in obese patients with abnormal glucose tolerance and positively correlated with BMI, waist circumference, fat mass, HbA1c, HOMA-IR, fasting triglycerides, and with inflammatory markers." (PMID 32878157, 2020).
acute respiratory distress syndrome (1 paper, 2025). Progressive and life-threatening pulmonary distress in the absence of an underlying pulmonary condition, usually following major trauma or surgery. "In patients with acute respiratory distress syndrome, serum ANGPTL4 levels were about 5.7-fold higher than in control subjects (p < 0.0001)." (PMID 40006981, 2025).
alcoholic fatty liver disease (1 paper, 2024). Lipid infiltration of the hepatic parenchymal cells that is due to alcohol abuse. "Silencing of PPARα aggravates lipid deposition and decreases the expression of ANGPTL4 in non-alcoholic fatty liver disease cells." (PMID 39088466, 2024).
anemia (1 paper, 2023). A reduction in the number of red blood cells, the amount of hemoglobin, and/or the volume of packed red blood cells. "ADAMTS18 and ANGPTL4 were also correlated with acidosis and severe anemia." (PMID 37788095, 2023).
Arrhythmia (1 paper, 2021). Any cardiac rhythm other than the normal sinus rhythm. "Ang II increased AF susceptibility and atrial fibrosis, and ANGPTL4 significantly attenuated Ang II-induced increase in arrhythmia, fibrosis, inflammation, and apoptosis in atrial tissue." (PMID 34422410, 2021).
arterial disease (1 paper, 2021). "In recent years, several studies have attempted to address the association between the ANGPTL4 SNPs and arterial disease in humans." (PMID 33750331, 2021).
asthma (1 paper, 2025). "Notably, high concentration of n-3 LCPUFA upregulated CPT1A and ANGPTL4, key genes involved in the PPAR signaling pathway, underscoring potential molecular mechanisms by which n-3 LCPUFAs may influence asthma susceptibility." (PMID 41149648, 2025).
bacterial meningitis (1 paper, 2019). Inflammation of the membranes surrounding the brain and spinal cord due to a bacterial infection. "However, this molecule has never been reported in bacterial meningitis, and the specific roles of ANGPTL4 during this pathogenic process is still unclear." (PMID 31766605, 2019).
bacterial pneumonia (1 paper, 2019). Acute infection of the lung parenchyma caused by bacteria (e.g., Streptococcus pneumoniae, Haemophilus influenzae, Chlamydia pneumoniae, Mycoplasma pneumoniae, and Legionella pneumophila). "To this end, we examined its impact on lung edema and tissue integrity during secondary bacterial pneumonia using ANGPTL4 knockout mice (ANGPTL4−/−) and immunoneutralization of cANGPTL4." (PMID 31164474, 2019).
blood pressure (1 paper, 2021). "The ANGPTL4 gene SNP rs1044250 is an independent risk factor for elevated blood pressure." (PMID 33593372, 2021).
brain injuries (1 paper, 2025). "Angiopoietin‐like protein 4 (ANGPTL4) is critical for vascular integrity and reducing inflammation in ischemic and hypoxic brain injuries." (PMID 39972951, 2025).
cerebral amyloid angiopathy (1 paper, 2024). "An autopsy study showed that increased ANGPTL4 expression was associated with increased cerebral microvessel density in patients with cerebral amyloid angiopathy, a phenomenon that may be caused by hypoxia." (PMID 39470400, 2024).
cerebral edema (1 paper, 2020). "Previous studies showed that ANGPTL4 can significantly inhibit the inflammatory response and alleviate neurological deficits and cerebral edema after ICH." (PMID 32210752, 2020).
cerebrovascular diseases (1 paper, 2014). "Recent studies on secreted Angptl4 focused mainly on lipid metabolism, tumor metastasis and cardiovascular or cerebrovascular diseases." (PMID 25165975, 2014).